OGT (O-linked N-acetylglucosamine (GlcNAc) transferase)
Diseases named in the same sentence as OGT in open-access papers (continued):
Sharing a sentence is not in itself a finding about the gene and the disease.
liver cancer (16 papers, 2015 to 2025). An epithelial or non-epithelial malignant neoplasm that arises from the liver. "In addition, we found that YAP and OGT were positively associated with cyclin-dependent kinase 19 (CDK19) in liver cancer tissues and cell lines." (PMID 34588426, 2021). "Additionally, the transcriptional regulator Yes-associated protein (YAP) strongly activates the OGT promoter in hepatic cancer cell lines." (PMID 30356686, 2018). "O‐GlcNAc expression was measured after 24 h of etoposide treatment, and the effect of O‐GlcNAc transferase (OGT) inhibition by OSMI‐1 on etoposide's anticancer activity in HepG2 human liver cancer cells was quantitatively analyzed." (PMID 40237201, 2025). "Our results are consistent with a report showing that blocking FASN with C75, a FASN inhibitor, reduces both OGT and O-GlcNAcylation levels in liver cancer cells." (PMID 38732103, 2024). "In liver cancer, pharmacological inhibition of OGT results in a decrease in the level of PD-L1, a key regulator highly expressed in some cancers enabling these cells to evade immune responses." (PMID 37838167, 2023). "Genetic inhibition of OGT reduces Yap expression in liver cancer cells but also blocks cancer cell proliferation, further highlighting the critical role of OGT and O-GlcNAc in regulating the expression and function of Yap in cancer." (PMID 37838167, 2023). "In this study, we revealed that HG positively regulates YAP and OGT expression to enhance the proliferative capacity of liver cancer cells." (PMID 34588426, 2021). "Collectively, these results demonstrate that CDK19 promoted cellular O-GlcNAcylation of liver cancer cells in an OGT-dependent manner." (PMID 34588426, 2021). "Through online analysis of the GEPIA database, we found that there was a significant correlation between the expression of CDK19 and OGT in liver cancer, with a correlation coefficient of 0.44." (PMID 34588426, 2021). "Here we found that OGT, the only known endogenous enzyme that catalyzes O-GlcNAcylation, was significantly upregulated in liver cancer tissues compared to adjacent normal tissues." (PMID 34588426, 2021). "Our results showed that HG promoted the expression of YAP and OGT in liver cancer cells and activated the HBP." (PMID 34588426, 2021). "The main goal of this study was to determine if OGT inhibition was able to enhance the therapeutic efficacy of DOX in the treatment of liver cancer." (PMID 33121131, 2020). "Here, we examined the therapeutic efficacy of the combination treatment of DOX and the OGT inhibitor OSMI-1 in liver cancer." (PMID 33121131, 2020). "We found that the combination treatment of doxorubicin (DOX) and O-GlcNAc transferase (OGT) inhibitor OSMI-1 has synergic therapeutic efficacy in the treatment of liver cancer." (PMID 33121131, 2020). "Similarly, corosolic acid inhibits liver cancer progression by decreasing OGT expression and O-GlcNAcylation levels in cancer cells." (PMID 39285476, 2024). "Similarly, inhibition of OGT and reduced O-GlcNAc levels in liver cancer synergistically improves the effect of doxorubicin in inducing apoptosis in cancer cells." (PMID 37838167, 2023). "Importantly, c-Jun is modified with O-GlcNAc at Serine residue 73, which is essential for the ferroptosis-inhibiting activity of c-Jun, suggesting a role of OGT and O-GlcNAc in suppressing ferroptosis to promote survival of liver cancer cells." (PMID 37838167, 2023). "As a kinase, CDK19 may inhibit the phosphorylation of OGT and thus promote O-GlcNAcylation in liver cancer cells." (PMID 34588426, 2021). "Altogether these results prove that the glucose/OGT/miR-483-3p signaling axis has an important role in the anti-apoptotic mechanisms of liver cancer and can be an important dowel to understand the oncogenic mechanisms that link metabolism to resistance to drugs and apoptosis." (PMID 28481368, 2017).
liver cancer (continued). "Similarly, inhibition of OGT expression in hepatocarcinoma cells by miR-15-a results in cell cycle arrest and accumulation of cancer cells in G0/G1 phases, which ultimately leads to impaired proliferation of liver cancer cells." (PMID 37838167, 2023). "The combination of OGT inhibitor OSMI-4 and PD-L1 mAb can restore tumor immunity and synergistically inhibit the growth of liver cancer and melanoma in fully immunized mice." (PMID 40760673, 2025). "For instance, in HCC, OGT highly O-GlcNAcylates speckle-type POZ protein (SPOP) at Ser96, facilitating its nuclear entry and inhibiting apoptosis of liver cancer cells." (PMID 39285476, 2024). "For example, astragalus polysaccharide reduces OGT levels and increases OGA levels in liver cancer cells, thereby downregulating O-GlcNAcylation and promoting doxorubicin-induced apoptosis." (PMID 39285476, 2024). "Moreover, the X-inactive-specific transcript (XIST)/miR-424-5p/OGT axis regulates RAF1 glycosylation, impacting liver cancer growth." (PMID 39285476, 2024). "This suggests that a positive feedback loop – OGT-Hipk-OGT – exists to maximize the nutrient sensing capacity and sustain Hipk buildup, similar to the feedback regulation between OGT and YAP reported in human pancreatic and liver cancer cells." (PMID 34240146, 2021). "Our previous research stated that, in an HG environment, after the level of YAP in liver cancer cells increased, global cellular O-GlcNAcylation could be upregulated through the regulation of Nudt9, SLC5A3, and OGT." (PMID 34588426, 2021). "Also, we found higher levels of YAP OGT, SLC5A3, Nudt9, and O-GlcNAcylation in liver cancer tissues than in peritumoral tissues." (PMID 34588426, 2021). "Therefore, we confirmed that CDK19 participates in the regulation of O-GlcNAcylation in liver cancer cells, specifically through YAP and OGT." (PMID 34588426, 2021). "However, CA reduced the expression of Nudt9, SLC5A3, OGT, YAP, and O-GlcNAcylation in liver cancer cells cultured in HG." (PMID 34588426, 2021). "In liver cancer cells, treatment with PuGNAc and GlcNAc enhanced YAP O-GlcNAcylation, and overexpression of OGT resulted in a similar enhancement of YAP O-GlcNAcylation, while knockdown of OGT led to suppression of YAP O-GlcNAcylation." (PMID 28474680, 2017). "In liver cancer cells, treatment with corosolic acid or inhibition of CDK19, a kinase that regulates proliferation in various cancers, results in reduced O-GlcNAc level and reduced expression of OGT and Yap ultimately leading to impaired cell proliferation as well as defective tumor growth." (PMID 37838167, 2023). "We found that the levels of OGT, YAP, and O-GlcNAcylation in liver cancer cells with CDK19 knockout were increased compared to those treated with CA alone, suggesting that CA downregulates global O-GlcNAcylation in liver cancer cells in a CDK19-dependent manner." (PMID 34588426, 2021).
bladder cancer (15 papers, 2013 to 2024). "A previous study demonstrated that a high mRNA level of OGT was associated with poor differentiation of bladder cancer cells." (PMID 30453909, 2018). "This study aimed to explore hyper-O-linked N-acetylglucosaminylation (O-GlcNAcylation) with an elevation of the expression of O-linked-β-N-acetylglucosamine transferase (OGT) in human bladder cancer." (PMID 30453909, 2018). "The present study testified that hyper-O-GlcNAcylation was associated with the upregulated OGT level in bladder cancer cells." (PMID 30453909, 2018). "In human bladder cancer, reducing hyper O-GlcNAcylation by OGT knockdown decreased the proliferation of bladder cancer cells in vitro, as well as tumour growth in vivo." (PMID 39474868, 2024). "OGT knockdown significantly enhanced the sensitivity of drug-resistant bladder cancer cells to these chemotherapy drugs." (PMID 39285476, 2024). "The protein stability of NUSAP1 decreases after knocking down OGT expression in HT-1376 and T24 cells to reduce O-GlcNAcylation, thus promoting bladder cancer cell apoptosis." (PMID 39285476, 2024). "Indeed, associations with high-OGT levels and an enhanced grade of tumor aggressiveness, heightened metastasis incidence, and poor prognosis were also identified in numerous cancers, including prostate, colorectal, ovary, breast, endometrium, pancreatic, and bladder cancers." (PMID 35356257, 2022). "Studies have found that OGT in urine is significantly different between early bladder cancer and advanced bladder cancer, so the content of OGT can be analyzed to classify bladder cancer." (PMID 32596162, 2020). "Studies have found that increased levels of O-GlcNAcylation or OGT are involved in the genesis and development of various tumors, including bladder cancer." (PMID 32174982, 2020). "The results advanced the understanding of the tumor-promoting effect of OGT and O-GlcNAcylation in bladder cancer." (PMID 30453909, 2018). "This study demonstrated that OGT knockdown pronouncedly increased the chemosensitivity of bladder cancer cells to cisplatin." (PMID 30453909, 2018). "This study aimed to demonstrate the expression and function of OGT and O-GlcNAc modification in bladder cancer." (PMID 30453909, 2018). "Reducing hyper-O-GlcNAcylation by OGT knockdown inhibited the proliferation of bladder cancer cells in vitro and xenograft tumor growth in vivo, triggered apoptosis, as well as led to cell cycle arrest." (PMID 30453909, 2018). "In brief, the results indicated that the si-OGT-induced downregulation of O-GlcNAcylation effectively drove autophagy in human bladder cancer cells." (PMID 30453909, 2018). "MTT assay was performed to detect the sensitivity of bladder cancer cells to cisplatin after OGT knockdown." (PMID 30453909, 2018). "Reducing hyper-O-GlcNAcylation by OGT knockdown facilitated the chemosensitivity of bladder cancer cells to cis-platinum." (PMID 30453909, 2018). "The OGT knockdown–induced reduction of hyper-O-GlcNAcylation suppressed the proliferation of bladder cancer cells in vitro and subcutaneous xenograft tumor growth in nude mice." (PMID 30453909, 2018). "The hyper-O-GlcNAcylation of bladder cancer cells was reduced by OGT knockdown and its effects on phenotypes were examined." (PMID 30453909, 2018). "Taken together, the data indicated that OGT knockdown attenuated the proliferation of bladder cancer cells probably due to apoptosis promotion and cell cycle inhibition." (PMID 30453909, 2018). "Immunohistochemical staining for OGT and O-GlcNAcylation was performed in 20 paired human bladder cancer and adjacent normal tissues, as well as in human bladder cancer tissue microarrays (N = 169)." (PMID 30453909, 2018). "It elucidated hyper-O-GlcNAcylation and deregulated expression of OGT in bladder cancer cells and clinical samples." (PMID 30453909, 2018). "The expression of OGT and the O-GlcNAcylation were upregulated in bladder cancer tissues and cell lines." (PMID 30453909, 2018).
bladder cancer (continued). "Subsequently, the results of MTT assay indicated that the OGT knockdown–mediated reduction of O-GlcNAcylation potently inhibited the growth of bladder cancer cells." (PMID 30453909, 2018). "In addition, downregulation of O-GlcNAcylation induced by OGT silencing results in cell cycle arrest, as well as the induction of autophagy and apoptosis, in bladder cancer cells." (PMID 33194731, 2020). "In summary, studies have shown that analysis of O-GlcNAcylation or OGT expression may be useful for the diagnosis of bladder cancer, and OGT may be used as a potential target for bladder cancer therapy in the future." (PMID 32596162, 2020). "Importantly, the depletion or knockdown of OGT influences the fusion of autophagosomes with lysosomes and stimulates autophagic flux in mammalian cells; OGT downregulation also effectively increases autophagy response to human bladder cancer cells." (PMID 31827688, 2019). "Interestingly, the Oncomine expression analysis based on previous studies also demonstrated that the expression of OGT was higher in bladder cancer tissues than in normal tissues, suggesting a higher level of O-GlcNAc modification in bladder cancer tissues." (PMID 30453909, 2018). "Therefore, the MTT assay was performed to detect the effects of OGT on the sensitivity of bladder cancer cells to cisplatin." (PMID 30453909, 2018). "O-GLcNAcylation in T24 and UMUC-3 cells was downregulated by OGT knockdown to determine whether O-GlcNAcylation affected the proliferation of bladder cancer cells." (PMID 30453909, 2018). "The result suggested that O-GlcNAcylation and expression of OGT increased in bladder cancer cells." (PMID 30453909, 2018). "The result suggested that the reduction of OGT could elevate the sensitivity of bladder cancer cells to cisplatin." (PMID 30453909, 2018). "A limitation of the present study was that the mechanism underlying the biological effects of OGT and O-GlcNAcylation in bladder cancer was not explored." (PMID 30453909, 2018). "Taken together, the findings indicated that the analysis of O-GlcNAcylation or expression of OGT might be useful in bladder cancer diagnostics, and OGT might be used as a potential target for bladder cancer therapy in the future." (PMID 30453909, 2018). "Additionally, the OGT mRNA level was even higher in the urine of bladder cancer patients with invasive or advanced stages (grade II and III) compared with those with early stages (grade I)." (PMID 27542217, 2016). "Moreover, a significant difference in OGT mRNA expression was observed between early and invasive bladder cancers." (PMID 25315705, 2015). "Therefore, the analysis of urinary content of OGA and OGT mRNA may be useful for bladder cancer diagnostics." (PMID 24918087, 2014). "Some authors have already proposed the measurement of OGT and OGA mRNA in urine as a diagnosis tool in bladder cancer." (PMID 29861440, 2018). "Bladder cancer T24 and UMUC-3 cells were transfected with LV-sh-OGT or LV-sh-NC and then treated with various concentrations of cisplatin for 48 h." (PMID 30453909, 2018). "O-GlcNAcylation levels in bladder cancer cells were altered through pharmacological or genetic manipulations: treating with 6-diazo-5-oxo-norleucine (DON) or thiamet-G (TG) or up- and downregulation of O-GlcNAc transferase (OGT) or O-GlcNAcase (OGA)." (PMID 32174982, 2020). "Extensively investigations had confirmed that elevated protein O-GlcNAcylation and changes of OGT and/or OGA expression has a clear functional role in many types of malignancies, including bladder cancer, lung cancer, prostate cancer, hepatocellular carcinoma and colon cancers." (PMID 27542217, 2016). "Moreover, OGT expression was significantly higher in grade II and III in comparison to grade I bladder cancer indicating a potential in prognosis." (PMID 24918087, 2014). "The authors concluded that measurement of OGT and OGA mRNA in urine might be an interesting parameter for the diagnosis bladder cancers." (PMID 23964270, 2013).
bladder cancer (continued). "However, no further studies about OGT and O-GlcNAcylation in bladder cancer have been reported to date." (PMID 30453909, 2018).
cervical carcinoma (15 papers, 2014 to 2024). A carcinoma arising from either the exocervical squamous epithelium or the endocervical glandular epithelium. "For instance, quercetin has been reported to induce cell death in cervical cancer by reducing the expression of OGT, overall O-GlcNAc, and O-GlcNAcylated AMPK." (PMID 39285476, 2024). "We found that O-GlcNAc and OGA increases with long-term TMG treatment in both SH-SY5Y neuroblastoma cells and HeLa cervical cancer cells while OGT decreases as expected." (PMID 37469955, 2023). "Cervical cancer can origin from persistent HPV lesions through the action of two HR HPV genes, E6 and E7 while HPV E6/E7 gene transcription can be upregulated by OGT though O-GlcNAc modification of HCF-1 in cervical cancer cells." (PMID 35432358, 2022). "OGT and sCLU expression are elevated in cervical cancer cell lines, and O-GlcNAc-induced up-regulation of sCLU leads to cisplatin resistance." (PMID 36059648, 2022). "Previously, HPV E6 was found to up-regulate the expression of OGT by elevating the transcription of the OGT gene in cervical cancer tissues." (PMID 34638625, 2021). "OGT expression in HeLa cervical cancer cells not only increased expressions of E6 and E7 oncoproteins but also promoted the HCF-1 mediated transcriptional activity of the E6/E7 promoter." (PMID 34485140, 2021). "In cervical cancer cells, another protein with enzyme function, O-GlcNAc transferase (OGT), was proven to be involved in EMT regulation." (PMID 31781477, 2019). "Western blot analysis showed that levels of O-linked N-acetylglucosamine (O-GlcNAc) and O-GlcNAc transferase (OGT) were increased in cervical cancer cells; these effects were reversed by metformin treatment." (PMID 31489252, 2019). "Here, we found that sCLU is significantly increased in cervical cancer cell lines, which have higher expression levels of O-GlcNAc and OGT than keratinocytes." (PMID 29435130, 2018). "We found that sCLU expression was increased in cervical cancer tissue, which had higher O-GlcNAc and OGT expression than normal cervical tissue." (PMID 29435130, 2018). "In this study, we found that OGT and sCLU expression were elevated in cervical cancer cell lines, and that sCLU expression is regulated by O-GlcNAcylation." (PMID 29435130, 2018). "Here, we confirmed that OGT overexpression and hyper-O-GlcNAcylation occur in cervical cancer cells." (PMID 29435130, 2018). "Together, these data suggest that OGT, O-GlcNAc, and sCLU expression is increased in cervical cancer cell lines and cervical cancer." (PMID 29435130, 2018). "This study demonstrates that levels of O-GlcNAcylation and OGT are elevated in cervical cancer cell lines." (PMID 29435130, 2018). "Western blot analysis revealed that O-GlcNAc and OGT levels were elevated in these three cervical cancer cell lines relative to a keratinocyte cell line, HaCaT." (PMID 29435130, 2018). "We found that O-GlcNAc modification of HCF-1 enhances transcriptional activity of E6 and E7, and OGT is required for cervical cancer progression." (PMID 27331873, 2016). "Together, these results suggest that OGT is required for the HCF-1-mediated E6/E7 transcriptional activation in cervical cancer cells." (PMID 27331873, 2016). "Consistently, we found that OGT deletion attenuates the growth and proliferation of cervical cancer cells." (PMID 27331873, 2016). "Overall, our finding that O-GlcNAc modification of HCF-1 increases E6 and E7 in cervical cancer cells and in vivo strongly suggests an important role for the nutrient sensor OGT in human cervical cancer." (PMID 27331873, 2016). "We found that depleting OGT with OGT-specific shRNA significantly decreased levels of E6 and E7 oncoproteins, and cervical cancer tumorigenesis, while OGT overexpression greatly increased levels of E6 and E7 oncoproteins." (PMID 27331873, 2016). "In addition, elevated OGT and O-GlcNAcylation are associated with increased cell proliferation and reduced cellular senescence in HPV-induced cervical cancer." (PMID 37519786, 2023).